ZNF707 (zinc finger protein 707)
Description:
May be involved in transcriptional regulation.
Synonyms: LOC101928160
Tractability: PROTAC: UniProt records ubiquitination sites on it.
Gene: Protein-coding gene on chromosome 8 (143,684,452 to 143,713,898, forward strand). Ensembl gene ENSG00000181135.
Subcellular location: Nucleus
Subcellular location (Human Protein Atlas): Nucleoplasm
Pathways (Reactome):
Gene expression (Transcription): Generic Transcription Pathway
Gene Ontology:
Molecular function: protein binding; DNA-binding transcription factor activity; RNA polymerase II cis-regulatory region sequence-specific DNA binding
Biological process: regulation of transcription by RNA polymerase II; regulation of DNA-templated transcription
Cellular component: nucleus
Genetic constraint (gnomAD): Loss-of-function variants: 7 observed, 11.42 expected, observed/expected ratio (o/e) 0.61, 90% interval 0.35 to 1.15. The upper end of that interval is the gene's LOEUF score, 1.15, which puts it in group 5 of 6, group 1 being the genes least tolerant of losing a copy. Missense variants: 519 observed, 486.6 expected, observed/expected ratio (o/e) 1.07, 90% interval 0.99 to 1.15. Synonymous variants: 221 observed, 194.43 expected, observed/expected ratio (o/e) 1.14, 90% interval 1.02 to 1.27.
Homologues: Orthologues: chimpanzee ZNF707 (98% identical), macaque ZNF707 (94% identical). Paralogues in human: ZFP57 (32% identical), ZNF333 (26% identical), ZKSCAN7 (25% identical), ZNF852 (25% identical), ZNF17 (25% identical), ZNF416 (25% identical), ZNF287 (25% identical), ZNF776 (24% identical), ZNF34 (24% identical), ZNF214 (23% identical), ZNF222 (23% identical), ZNF527 (23% identical), and 38 more.
Diseases named in the same sentence as ZNF707 in open-access papers:
ZNF707 is named in the same sentence as 5 diseases in open-access papers, as found by Europe PMC text mining. Sharing a sentence is not in itself a finding about the gene and the disease. The quoted sentences say what the papers report.
breast carcinoma (1 paper, 2022). "Interestingly, one of the 14 secreted CanCord34 genes, ZNF707, has not previously been studied in breast cancer." (PMID 36497066, 2022).
clear cell renal cell carcinoma (1 paper, 2020). "This prognostic power was consistently observed in The Cancer Genome Atlas (TCGA) clear cell renal cell carcinoma dataset, suggesting that ZNF707 may have prognostic value in clear cell histology regardless of tissue origin." (PMID 32316112, 2020).
endometriosis (1 paper, 2020). The growth of functional endometrial tissue in anatomic sites outside the uterine body. "Given that endometriosis increases the risk of Ov-CCA, ZNF707 may play a functional role in tumorigenesis of endometriosis-associated Ov-CCA." (PMID 32316112, 2020).
cancer (4 papers, 2019 to 2023). A tumor composed of atypical neoplastic, often pleomorphic cells that invade other tissues. "The literature shows that some KZNFs are up-regulated in cancer, including ZNF695, ZNF320, ZNF200, ZNF354A, ZNF707, ZNF138 and so on." (PMID 37370088, 2023). "Although further investigation is needed, rs4873815-TT/ZNF707 may also have a prognostic power in clear cell histology regardless of cancer tissue." (PMID 32316112, 2020).
tumor (1 paper, 2019). "Mean expression of ZNF714 was similar in normal and tumor samples, whereas ZNF525, ZNF643, and ZNF707 fell below the detection level." (PMID 30444046, 2019).